EPCIP (exosomal polycystin 1 interacting protein)
Description:
Likely to be involved with PKD1 in the detection, sequestration and exocytosis of senescent mitochondria.
Synonyms: C21orf120; C21orf62; CU062; B37; PRED81
Tractability: Antibody: UniProt places it where antibodies can reach, with high confidence; UniProt predicts a signal peptide or a membrane-spanning region; its Gene Ontology location is reachable by antibodies, with medium confidence.
Gene: Protein-coding gene on chromosome 21 (32,790,673 to 32,813,743, reverse strand). Ensembl gene ENSG00000205929.
Subcellular location: Vesicle; Secreted, extracellular exosome
Gene Ontology:
Molecular function: identical protein binding; protein binding
Biological process: mitocytosis
Cellular component: extracellular exosome; migrasome; vesicle; extracellular region
Genetic constraint (gnomAD): Loss-of-function variants: 13 observed, 12.3 expected, observed/expected ratio (o/e) 1.06, 90% interval 0.69 to 1.65. The synonymous counts are far from expectation, so gnomAD's model fits this gene poorly and the ratio says little. Missense variants: 222 observed, 285.61 expected, observed/expected ratio (o/e) 0.78, 90% interval 0.7 to 0.87. Synonymous variants: 79 observed, 110.48 expected, observed/expected ratio (o/e) 0.72, 90% interval 0.6 to 0.86.
Homologues: Orthologues: chimpanzee EPCIP (95% identical), macaque EPCIP (94% identical), dog EPCIP (80% identical), pig EPCIP (77% identical), rabbit EPCIP (74% identical), mouse Epcip (68% identical), rat Epcip (68% identical), guinea pig EPCIP (66% identical), tropical clawed frog epcip (48% identical).
Diseases named in the same sentence as EPCIP in open-access papers:
EPCIP is named in the same sentence as 4 diseases in open-access papers, as found by Europe PMC text mining. Sharing a sentence is not in itself a finding about the gene and the disease.
EPCIP shares sentences with these, for which no sentence is quoted: tumor (2 papers); cyst (1); dyslexia (1); glioma (1).